MUC13 (mucin 13, cell surface associated)
Diseases named in the same sentence as MUC13 in open-access papers (continued):
Sharing a sentence is not in itself a finding about the gene and the disease.
MUC13 also shares sentences with these, for which no sentence is quoted: Diarrhea (2 papers); gastro-intestinal tumors (2); bacterial infections (1); benign ovarian tumors (1); breast carcinoma (1); cervical adenocarcinoma (1); chronic cystitis (1); colon adenocarcinoma (1); diabetes (1); digestive system cancer (1); gastroesophageal junction adenocarcinoma (1); genitourinary cancers (1); giardiasis (1); glioblastoma (1); head and neck squamous cell carcinoma (1); infectious disease (1); Intestinal Diseases (1); ischemia (1); lung adenocarcinoma (1); lung squamous cell carcinoma (1); lupus nephritis (1); Lyme disease (1); metabolic disorders (1); metastatic cancer (1); mucinous colorectal adenocarcinoma (1); ovarian clear cell cancer (1); pancreatic ductal adenocarcinoma (1); Parkinson’s (1); prostate adenocarcinoma (1); pseudomyxoma peritonei (1).
A further 5 diseases each share a sentence with MUC13 in 1 paper.